TRIM29 (tripartite motif containing 29)
Diseases named in the same sentence as TRIM29 in open-access papers (continued):
Sharing a sentence is not in itself a finding about the gene and the disease.
cancer (continued). "We saw significant transcriptional changes including the downregulation of key markers like EGR1 and CD24, whose reduced expression is linked to increased invasiveness and drug resistance and identified proteins such as TRIP6 and TRIM29 that enhance (cancer stem cells) CSC-like properties." (PMID 40946111, 2025). "In addition, the role of TRIM29 (Tripartite Motif Containing 29) has been highlighted in several human cancers, where it can function as an oncogene, promoting tumor growth and metastasis." (PMID 39497715, 2024). "Given the critical role of TRIM29 in regulating innate immunity and cancer, it is a worthwhile direction for in-depth research to explore whether m6A modification can regulate TRIM29 expression to influence innate immune responses in HNC." (PMID 39403369, 2024). "Furthermore, pancancer analysis of 33 cancer types in TCGA revealed that TRIM29 expression positively correlated with ZNF750 and KRT5 levels in most cancer types." (PMID 37365152, 2023). "Furthermore, the TRIM29 mRNA levels in multiple cancer types were also analyzed through the Oncomine platform." (PMID 37365152, 2023). "A compelling body of evidence has suggested that TRIM29 might have oncogenic behavior in bladder, colorectal, and pancreatic cancers." (PMID 35845310, 2022). "Overall, TRIM29 may have a pertinent function in the carcinogenesis of various human malignant tumors and be a useful biomarker for predicting the prognosis of patients." (PMID 36568638, 2022). "Effect and expression of TRIM29 proteins in different cancers." (PMID 34988104, 2021). "tripartite motif-29 (TRIM29) has been reported as oncogene in several human cancers." (PMID 34353343, 2021). "So the high expression of TRIM29 disrupts the function of NK cells, which may contribute to the development of cancer." (PMID 33495406, 2021). "Three main pathways have been identified where TRIM29 contributes to cancer formation." (PMID 34988104, 2021). "Additionally, LINC00324 knockdown down-regulated the levels of TRIM29 in PTC cells, and TRIM29 overexpression markedly abolished LINC00324-knockdown- or miR-195-5p-overexpression-mediated cancer-inhibiting effects." (PMID 33318312, 2020). "The better understanding of functions of TRIM29 may facilitate establishment of new cancer treatments." (PMID 33017104, 2020). "The abnormal expression of TRIM29 is controversial whether it promotes or suppresses cancer development." (PMID 32994394, 2020). "Furthermore, it is reported that expression of TRIM29 leads to suppression of anchorage-independent growth (AIG) in multiple cancer cell lines, contributing to poor outcome in cancer patients." (PMID 29552313, 2018). "TRIM29 might play an essential role in carcinogenesis of multiple human malignant neoplasms and could serve as a biomarker for the prediction of patients’ prognosis." (PMID 29552313, 2018). "TRIM29 has been found to be upregulated in various cancer tissues." (PMID 29552313, 2018). "Increasing evidence shows that TRIM29 is involved in a variety of cancers." (PMID 29038422, 2017). "TRIM29 mainly acts as an oncogene in most tumors and also may function as a tumor suppressor in few cancers, which should be further confirmed." (PMID 27081037, 2016).
cancer (continued). "Studies show that TRIM29 has been involved in a variety of cancers." (PMID 27081037, 2016). "Several studies have shown that TRIM29 plays an important role in the various types of cancers." (PMID 27145374, 2016). "It suggests that TRIM29 has tissue specific multifaceted functions upon transformation to cancer." (PMID 24651077, 2014). "Thus, over-expression of TRIM29 was observed in many human cancers including pancreatic cancer, where it enhanced tumor growth through stabilization of beta catenin." (PMID 24651077, 2014). "Interestingly, TRIM29 was differentially regulated in the respective carcinomas as well, but in the reverse direction." (PMID 24651077, 2014). "In contrast, TRIM29 could suppress tumorigenesis in other cancer types." (PMID 37365152, 2023). "Thus, TRIM29 has a complex role depending on the type of cancer and the microenvironment, and its role in ESCA remains unclear." (PMID 37365152, 2023). "For instance, targeting TRIM29 may sensitize refractory cancers to therapies." (PMID 33017104, 2020). "In the light of this, the prognostic value of TRIM29 may vary in different cancers." (PMID 29552313, 2018). "Of special interest, for TRIM29 it was previously reported that it could either function as a tumor suppressor in luminal ER positive breast cells or as an oncogene in pancreatic, lung and various other cancers." (PMID 24651077, 2014). "All other coding genes LPHN2, EFNA1, ISL1, TRIM29, PAWR, and GOSR2 were differentially up- or downregulated in different cancers." (PMID 36352089, 2022). "In fact, EGFR was part of a cluster of dysregulated genes and enriched gene sets in the FIR20 cells that define the basal breast (cancer) subtype (LAMC2, TRIM29, COL17A and cytokeratin genes (KRT6, KRT7, KRT13, KRT15))." (PMID 35579852, 2022). "Extensive genes have been identified as the target of miR-761 in numerous cancers, including HDAC1, Rab3D, Runx3, Mitofusin-2, CXCR1, TRIM29, MSI1, ING4, TIMP2, and GSK3β." (PMID 32185226, 2020). "Therefore, TRIM29 may have the different roles in different types of cancer." (PMID 27081037, 2016). "Secondly, TRIM29, a member of tripartite motif (TRIM) family, is located on chromosome 11q23 and was reported to be upregulated in multiple types of cancers including pancreatic, gastric, bladder, ovarian and colorectal." (PMID 25797263, 2015). "Given the critical roles of TRIM29 and TRIM18 in controlling cGAS-STING pathway and cancer development, it is deserved to investigate the role of TRIM29 and TRIM18 in controlling cGAS-STING pathway in cancers." (PMID 40552295, 2025). "Furthermore, TRIM29-mediated STING ubiquitination degrades STING in immune and cancer cells, and its overexpression hinders immune responses." (PMID 40028324, 2025). "Even though the dysregulation of TRIM29 protein in cancer has not been fully elucidated, there are some common conditions that provide evidence for the multifaceted roles of TRIM protein." (PMID 34988104, 2021). "TRIM29 regulates the choice of DNA DSB repair pathway by facilitating 53BP1 accumulation to promote NHEJ and may have potential for development into a therapeutic target to sensitize refractory cancers or as biomarker of personalized therapies." (PMID 33017104, 2020).
tumor (54 papers, 2007 to 2026). "When TRIM29 was restored with UAB116 treatment, the active forms of β-catenin were decreased, implying a tumor suppressor function for TRIM29 that is associated with β-catenin signaling in HB." (PMID 40362175, 2025). "Another overexpressed gene in our study, TRIM29, is also associated with tumor cell proliferation and migration." (PMID 36673815, 2023). "With reference to the finding that low TRIM29 expression is closely associated with poor prognosis in cSCC, it stands for promising therapeutic targets and modern tumor markers for early identification and risk evaluation." (PMID 34988104, 2021). "It would be interesting to investigate the role of TRIM29 that has been implicated in blocking pathogenesis, be it by maintaining the epithelial fate, as a tumor suppressor, or in preventing neurodegenerative disorders." (PMID 29228692, 2017). "Increased expression of TRIM29 is associated with tumor differentiation, tumor growth, tumor invasion, and lymph node metastasis." (PMID 22276141, 2012). "Furthermore, elevated TRIM29 expression is associated with tumor growth and proliferation via the regulation of cyclin E in esophageal SCC patients." (PMID 34988104, 2021). "We analyzed tumor recurrence associated with high TRIM29 expression by combining DFS and RFS." (PMID 29552313, 2018). "TRIM29 overexpression reduces chemotherapy response whereas TRIM29 knockout not only increases chemosensitivity but also reduces TNBC tumor growth." (PMID 40420099, 2025). "TRIM29 knockout reduces TNBC tumor growth and tumor-dissociated cells maintain TRIM29 knockout status as well as exhibit similar functional alterations as chemoresistant TNBC cells." (PMID 40420099, 2025). "P63 has been shown to regulate the expression of TRIM29 and is responsible for driving tumor formation and invasion in Ba/Sq MIUC tumors." (PMID 40643470, 2025). "Xu and colleagues showed that silencing of TRIM29 leads to the activation of Wnt/β-catenin signaling, suggesting that TRIM29 is inhibiting Wnt/β-catenin signaling, thereby functioning as a tumor suppressor." (PMID 40362175, 2025). "Tumor-dissociated cells maintain TRIM29 knockout status as well as exhibit similar functional alterations as chemoresistant TNBC cells." (PMID 40420099, 2025). "Previous studies have shown that TRIM29 participates in the occurrence and development of a variety of tumours by regulating biological processes such as cell proliferation, apoptosis, invasion, and migration." (PMID 37671092, 2023). "Mechanistically, TRIM29 functioned as a positive regulator of tumor suppressor gene ZNF750 via modulating IL6/STAT3 signaling pathway." (PMID 37365152, 2023). "Taken together, these data indicate that TRIM29 acts as a tumor suppressor to inhibit the proliferation of ESCC." (PMID 37365152, 2023). "Mechanistically, TRIM29 downregulation suppresses the expression of the tumor suppressor ZNF750 by activating the STAT3 signaling pathway." (PMID 37365152, 2023). "Collectively, all these results suggest a model for how TRIM29 acts as a tumor suppressor via modulating ZNF750 expression in ESCC." (PMID 37365152, 2023). "TRIM29 has been reported to have contextual function of tumor suppression or oncogenic depending on the tumor type." (PMID 35845310, 2022). "Tripartite Motif Containing 29 (TRIM29) has been reported to function as an oncogene or a tumor suppressor depending on the tumor type." (PMID 35845310, 2022). "One of the mechanisms of the tumor suppressive activity of miR-185 is related to its ability to directly suppress the TRIM29-Wnt/β-catenin signaling axis." (PMID 36287119, 2022). "While TRIM29 seems to serve as a tumor-suppressive factor in breast cancer and hepatocellular carcinoma, it has shown an oncogenic feature in other types of malignancies such as ovarian and cervical cancers." (PMID 35845310, 2022). "TRIM29 has also been reported to function as an oncogene or a tumor suppressor depending on the tumor type." (PMID 35845310, 2022).
tumor (continued). "The tumor suppressor gene TRIM29 is up regulated during early and late embryonic bladder development but is down-regulated in three different bladder cancers." (PMID 36352089, 2022). "TRIM29 is a transcription factor that has shown oncogenic or tumor-suppressive activities dependent on the tumor type." (PMID 36287119, 2022). "Our results showed that the TRIM29 expression was detected in the tumours obtained from patients with PC, compared with the corresponding non-tumour tissues." (PMID 34353343, 2021). "The qPCR results revealed that TRIM29 expression was significantly higher in tumor tissues than in paired normal tissues (P<0.05) and was much more highly expressed in RSCC than in LSCC (P<0.0001)." (PMID 33495406, 2021). "Among the 50 specimens of tumour tissues, the protein expression of TRIM29 was significantly increased in 37 specimens." (PMID 34353343, 2021). "This evidence potentially supports the dual effect of TRIM29, which can act as either an oncogene or a tumor suppressor gene, depending on the tumor type." (PMID 34988104, 2021). "Our findings suggest that TRIM29 acts as a tumor promoter in CRC, especially in RSCC, and is a potential therapeutic target for CRC treatment." (PMID 33495406, 2021). "The expression of TRIM29 was significantly higher in PC tissues than in the adjacent non-tumour tissues." (PMID 34353343, 2021). "TUNEL analysis further confirmed that TRIM29 knockdown increased the number of apoptotic cells in xenograft tumours." (PMID 34353343, 2021). "As TRIM29 acts as a double-edged sword for tumor growth, it remains to exert important effects in both the occurrence and the development of tumors." (PMID 33824865, 2021). "Depending on the target of the specific TRIM protein, increased expression of certain TRIM family members (e.g., TRIM25, TRIM27, and TRIM29) in tumor tissue promotes oncogenesis, and this has been correlated with poor clinical outcomes." (PMID 34988104, 2021). "Compared with tumors in the lenti-NC group, tumors in the lenti-shTRIM29 group grew more slowly, which resulted in smaller tumor masses, and exhibited lower levels of TRIM29 and Ki67, and tumors in the lenti-pTRIM29 group got the opposite results." (PMID 33495406, 2021). "The expression of TRIM29 was significantly related to histological grade, tumor size, tumor invasion range and lymph node metastasis." (PMID 32640423, 2020). "In turn, TRIM29 induced K48-linked ubiquitination of STING for protein degradation, which enhances EBV-positive tumor cell survival." (PMID 32632113, 2020). "The authors identified that P63 was responsible for regulating TRIM29 expression as part of a basal gene program and was a major driver of tumor formation." (PMID 32822399, 2020). "Recent studies have revealed that TRIM29 exert important effects in tumor cell invasion and metastasis." (PMID 29552313, 2018). "It has been also reported that TRIM29 acts as a tumor suppressor through inhibiting Twist-related protein 1 (TWIST1) and suppress epithelial mesenchymal transition (EMT)." (PMID 29552313, 2018). "In HCC, the mechanism of TRIM29 tumor suppression is related to Wnt/β-catenin signaling." (PMID 40362175, 2025). "TRIM29 is an oncoprotein and a major driver of tumor formation/invasion in UC." (PMID 40643470, 2025). "The TRIM29 protein is the product of the ataxia telangiectasia group D complementation (ATDC) gene, which has been found to be associated with a variety of biological processes, such as tumor progression and transduction of DNA damage signal." (PMID 38213743, 2024). "Moreover, results of subcutaneous xenograft models further confirmed that TRIM29 silencing significantly reduced tumor growth." (PMID 39768197, 2024). "However, another study indicated that miR-424-5p, a tumor-suppressor miRNA, targets the TRIM29 gene and reverses its oncogenic effects." (PMID 34988104, 2021). "Conversely, new evidence points to the tumor-suppressive effect of TRIM29 in cSCC." (PMID 34988104, 2021).
tumor (continued). "TRIM29 reactivity was observed in 66.04% (77/126) of the PC specimens collected at our center, while a negative staining was observed in the corresponding adjacent non-tumour tissues." (PMID 34353343, 2021). "TRIM29 is highly expressed in many tumors and promotes tumor growth." (PMID 33824865, 2021). "TRIM29 may also enhance tumor progression and metastasis by interaction with β-catenin and modifying E-cadherin autophagy degradation." (PMID 34988104, 2021). "TRIM29 possesses a tumor-suppressor feature via inhibition of the Wnt/β-catenin signaling pathway." (PMID 34988104, 2021). "In the case of TRIM29, the direct tumor promoting effects by TRIMs on CRC could be clearly assigned to an induction of EMT." (PMID 33066016, 2020). "Tumor suppressive miR-449a inhibited PDAC cell aggressiveness through targeting TRIM29." (PMID 30866526, 2019). "In summary, we concluded that TRIM29 in tumor tissues might be effective indicator for predicting prognosis and tumor progression in the future." (PMID 29552313, 2018). "Therefore, it is necessary to conduct a meta-analysis to summarize the findings globally and clarify the preliminary predictive value of TRIM29 in tumor prognosis." (PMID 29552313, 2018). "However, a few studies revealed that TRIM29 acts as a tumor suppressor in breast cancer cell lines by inhibiting TWIST1 and epithelial-mesenchymal transition (EMT)." (PMID 27081037, 2016). "Taken together, these findings suggest that TRIM29 is involved in the estrogen receptor pathway and may have tumor suppressor activity in luminal mammary cells." (PMID 24651077, 2014). "Overall, these studies showed that TRIM29 could function either as an oncogene or as a tumor suppressor gene in various epithelial tissues." (PMID 24651077, 2014). "A second basal/myoepithelial cluster highly expressed in Group III and IV tumors and a subset of DMBA tumors with squamous morphology was characterized by high expression of ID4, TRIM29, and Keratin 5, the latter of which is another human basal-like tumor marker." (PMID 17493263, 2007). "However, while high expression of TRIM29 is associated with worse OS in digestive system cancers, low expression of TRIM29 is associated with favorable OS in multiple tumors, indicating that TRIM29 may also act as a tumor suppressor gene." (PMID 29552313, 2018). "In another study, hsa-miR-432 has been shown to act as a tumor suppressor gene by targeting LRP6, TRIM29, and Pygo2, thus deactivating the Wnt pathway." (PMID 38326829, 2024). "In vivo, TRIM29 knockdown in a subcutaneous xenograft model using BALB/c nude mice also reduced β-catenin levels and suppressed tumor growth." (PMID 39768197, 2024). "However, the specific role of TRIM29 may differ in different tumours." (PMID 37671092, 2023). "Together, these data argue that CARM1 regulates SCLC tumor growth via methylation of NFIB R388 and the subsequent recruitment of the methylation reader TRIM29." (PMID 36690626, 2023). "In summary, this study explores the oncosuppressive function of TRIM29 in ESCC and reveals that TRIM29 downregulation due to hypermethylation of its promoter, positively regulates tumor suppresser gene ZNF750 via modulating IL6/STAT3 signaling pathway." (PMID 37365152, 2023). "Based on the results of qRT-PCR and the immunohistochemical analyses of the cell lines and the FFPE tissues from the synchronous collision tumor, we finally identified two novel MPM marker genes, PHGDH and TRIM29." (PMID 35204409, 2022).